TNF (tumor necrosis factor)
Diseases named in the same sentence as TNF in open-access papers (continued):
Sharing a sentence is not in itself a finding about the gene and the disease.
Anorexia (114 papers, 2007 to 2025). Lack of desire to eat (loss of appetite). "Elevated levels of pro-inflammatory cytokines—IL-6, TNF-α, IL-1β—have been observed in depressed patients and are associated with sickness behavior (anhedonia, fatigue, anorexia), overlapping with depressive symptoms." (PMID 40927563, 2025). "High blood TNF-α levels cause an increase in basal energy expenditure, anorexia, and loss of muscle and bone mass in older men and women." (PMID 36985374, 2023). "Systemic administration of cytokines, such as TNF and IL-18, were shown to cause anorexia by directly targeting receptors in the central nervous system, most notably in the Stria Terminalis." (PMID 34835051, 2021). "A number of cytokines have been previously linked to anorexia, including IL-6, TNF-α, CXCL8, IL-1β, IL-18, IL-2, and IFN-γ." (PMID 32071269, 2020). "It is known that TNF-α and IL1β, are cytokines that mediates symptoms of sickness such as anorexia, immobility and body weight loss." (PMID 30133465, 2018). "Cachexia is distinct from starvation or malabsorption and can be accompanied by anorexia, elevated inflammatory cytokines (IL-1, IL-6 and TNF-α), loss of fat and insulin resistance." (PMID 30379866, 2018). "Potent anti-inflammatory effects of ghrelin were reported on the expression of IL-1β, IL-6, and TNFα in the liver, spleen, lungs, and mesenteric lymph nodes of LPS-treated mice associated with an attenuation of the LPS-induced anorexia." (PMID 26681840, 2015). "TNF-α has been linked to increased resting energy expenditure and anorexia." (PMID 40106024, 2025). "The release of pro-inflammatory cytokines, including TNF-α, IL-6, and IL-1, is provoked by cancer cells, which sets off a chain reaction that results in weight loss by causing the breakdown of skeletal muscle and adipose tissue as well as anorexia." (PMID 38466657, 2024). "Increased TNF-α could, thus, be a weight-loss supporting and potentially mostly proinflammatory anorexia-maintaining factor, especially during acute starvation." (PMID 36061277, 2022). "We could find no studies that reported associations between osteopontin and anorexia, although Lönnerdal and colleagues reported lower TNF-α in infants fed formula fortified with osteopontin compared with standard formula." (PMID 34084993, 2021). "It is also known that high level of cytokines TNFα, IL-6, and IL-2 are associated with a decrease in food intake and may contribute to anorexia." (PMID 32297262, 2020). "Furthermore, inflammatory mediators, such as interferon-gamma (IFN-γ), interleukin-6 (IL-6) and tumor necrosis factor-alpha (TNF-α) may contribute to anorexia, adipose tissue loss and muscle atrophy." (PMID 22761662, 2012). "GDF15 is secreted by a range of tissues, including the liver, inguinal WAT and BAT, and can contribute to sickness‐induced anorexia independently of TNFα, via direct signalling in the hindbrain." (PMID 39428707, 2025). "For instance, in the hypothalamus, a brain region that controls food intake, TNFα inhibits orexigenic AgRP neurons and activates anorexigenic proopiomelanocortin (POMC) neurons, promoting inflammation-associated anorexia." (PMID 39958993, 2025). "Cytokines such as IL-1, IL-6 and TNF-α play central roles in orexia regulation, often promoting anorexia by activating mechanisms that inhibit appetite." (PMID 40046187, 2024). "Intracerebroventricular (ICV) injection of TNFα or IL‐1β at pathophysiological levels—aiming to administer the cytokines directly to the central nervous system—induces anorexia." (PMID 38414161, 2024). "TNF‐α is a well‐studied pro‐inflammatory cytokine understood to induce anorexia peripherally and centrally by inhibiting the secretion of ghrelin, and to trigger muscle wasting through activation of the NF‐kappa B pathway." (PMID 38481033, 2024). "For IL-6, and TNFα, the literature supports relationships of these markers with anorexia and skeletal muscle breakdown." (PMID 37906352, 2023).
Anorexia (continued). "TNF and IL-6, both known contributors to oral premalignant conditions and oral malignancies, have been observed to induce anorexia in affected individuals." (PMID 38169924, 2023). "Tumour-driven cytokines, such as growth differentiation factor 11, IL-1β, IL-6 leukaemiaia inhibitory factor, TNF-α, and TGFβ1 promote cancer cachexia with anorexia in the brain, proteolysis in the skeletal muscles, and browning in the WAT." (PMID 35406121, 2022). "TNFα promotes a catabolic state by inducing anorexia and engendering both protein degradation and suppression of their synthesis." (PMID 35883745, 2022). "In hamsters, TNF and IL-1β produced in response to LPS administration were shown to increase leptin expression in adipose tissue and induce anorexia." (PMID 34835051, 2021). "TNF-α mediated anorexia and decreased DMI are important features of the APR since nutrient and energy intake are reduced simultaneously with consequences not only for electrolyte balance but also for the entire metabolism." (PMID 33435209, 2021). "Within these pathways, many cell cytokines, including those associated with inflammation, such as IL-1, IL-6, TNF-10, IL-22, and TNF-alpha, contribute to the anorexia of cancer patients." (PMID 34724970, 2021). "In LPS- or TNF-α-induced anorexia experimental models of acute inflammation, NPY expression in the hypothalamus is reduced, consistent with the observed decrease in food intake." (PMID 34899611, 2021). "Among TNF-α, TGF-β, and IL-6, the post-/pretreatment ratio of TGF-β after 12 weeks was associated with TKI-induced anorexia, and the ratios after 10 and 12 weeks were associated with fatigue." (PMID 33050250, 2020). "Increases in IL-1β and TNF contribute to anorexia, and TNF and IL-6 promote lipolysis and inhibit lipogenesis in WAT leading to weight loss." (PMID 32934774, 2020). "Signaling downstream of PRR elicits the production of interleukins (IL), such as IL-1, IL-6, IL-8, or tumor necrosis factor (TNF), which signal systemically to induce anorexia of infection as well as to regulate glucose metabolism." (PMID 30425714, 2018). "Elevations of IL-1β, IL-6, and TNF-α were observed in DON-administered mice that were correlated to DON-induced anorexia." (PMID 29710820, 2018). "Gaigé and co-workers indicated that T-2-induced anorexia correlated with IL-1β, IL-6, and TNF-α mRNA upregulation in the spleen and liver." (PMID 29710820, 2018). "Cachexia is usually accompanied by anorexia and related to overproduction of pro-inflammatory cytokines, such as interleukins and tumor necrosis factor (TNF)." (PMID 29802455, 2018). "Cachexia often appears with anorexia as a result of imbalances between pro-inflammatory (e.g., TNF-α, IL-1, IL-6, interferon-gamma [IFN-γ]) and anti-inflammatory cytokines (e.g., interleukin-4 [IL-4], interleukin-12 [IL-12], interleukin-15 [IL-15])." (PMID 28177923, 2017). "This has been attributed to decreased oral intake due to anorexia (perhaps due to systemic circulation of pro-inflammatory cytokines such as TNF), early satiety, nausea, or pain." (PMID 27045690, 2016). "In summary, our results shown that in the hypothalamus of sedentary tumour-bearing animals increase in TNF-α and IL-1β levels exacerbated the disturbances that affect the reduction of food intake and worsened the framework of cancer-induced anorexia." (PMID 21861927, 2011). "This is relevant because in a previous study, TNFα promoted anorexia in rodents while IL-1β promoted motivational changes, including increased social withdrawal behavior." (PMID 21167054, 2010). "Therefore, it is likely that during infection, TNFα contributes to sickness‐induced anorexia by signalling through adipocytes to modulate adipokine expression and alter feeding behaviour." (PMID 39428707, 2025). "For instance, IL‐6, TNFα and IL‐1 act directly on the brain to enhance anorexia." (PMID 38414161, 2024).
Anorexia (continued). "Studies using experimental models show clearly that the proinflammatory cytokines, including IL-1, IL-6, and TNFα are intermediaries of anorexia and that fatigue, poor functionality, and a poor QoL are also factors related to these inflammatory markers, predicting overall survival and prognosis." (PMID 38744744, 2024). "Johnson suggested the TNF-α induced anorexia behavior of hosts." (PMID 37143119, 2023). "The production of proinflammatory cytokines is induced by infectious factors, and higher TNF-α, IL-1β and IL-6 levels affect the surrounding organs to induce disease behavior and inflammation-related anorexia, which participate in the induction of disease behavior." (PMID 34899611, 2021). "Recent studies suggest that tumor necrosis factor α and interleukin 1β, especially in AgRP-producing neurons, might contribute to inflammation-induced anorexia during acute inflammatory conditions." (PMID 34840970, 2021). "Our findings indicate that the effect of TNF-α and IL-1β, especially on the activity of AgRP-producing neurons, may contribute to inflammation-induced anorexia observed during acute inflammatory conditions." (PMID 33255553, 2020). "TNF induces anorexia via peripheral and central nervous system mechanisms." (PMID 32843714, 2020). "They supposed that high TNF-α level may induce anorexia and energy expenditure, which may be explainable for body weight reduction." (PMID 31652851, 2019). "In this context, it has been shown that CCK and interleukin-1 (IL-1) may synergize to worsen anorexia and that TNF-α may interfere with the orexigenic effect of neuropeptide-Y (NPY)." (PMID 31191339, 2019). "This anorexigenic effect of TNFα and IL-6 showed to coincidence with increased hypothalamic serotonergic activity, providing further evidence for a role for serotonin in inflammation-induced anorexia." (PMID 27207102, 2016). "TNFα and IFNγ have been shown to play an important role in LPS-induced anorexia." (PMID 26734008, 2015). "Additionally, a study using the dehydration-induced anorexia model, elevated levels of the inflammatory markers were reported (TNF-α, IL-6, and IL-1β), suggesting the possibility of an environment conducive to neuroinflammation with suggested correlation with neurodegeneration." (PMID 40269196, 2025). "Studies suggest the cytokines IL-1β and TNF-α play a role in the neuroendocrine regulation of appetite as increased levels of these cytokines in the brain are associated with a greater incidence of anorexia in mouse models, and inhibition of TNF-α in rats was shown to forestall anorexia." (PMID 38254849, 2024). "Interestingly, FAM19A5 knockdown led to the reduction of TNF-α-induced anorexia and decreased loss of body weight, whereas administration of FAM19A5 by an intracerebroventricular route resulted in anorexia, body weight loss, hyperthermia, and the enhanced expression of inflammatory factors." (PMID 35712659, 2022). "Indeed, cytokines (e.g., TNF-a, IL-1a, IL-1b and IL-6) can directly cause neuronal apoptosis and produce a stereotyped cluster of nonspecific signs such as impaired concentration, anorexia, fatigue, diminished motivation, depression, and anorexia." (PMID 35964069, 2022). "In addition, inflammatory markers, such as IL1, IL6 and TNF-α which are known to induce anorexia or may have stronger impact on appetite and food intake compared with CRP, were not measured in the present study." (PMID 32618518, 2020). "Therefore, it might be speculated that anorexia induction by trichothecenes could be mediated by the pro-inflammatory cytokines IL-1β, IL-6, and TNF-α as part of sickness behavior." (PMID 29710820, 2018). "Cancer anorexia also appears to be significantly influenced by increased inflammatory status, as demonstrated by increased brain levels of proinflammatory cytokines such as interleukin-1 (IL-1) and tumor necrosis factor-α (TNFα) in experimental models of cancer anorexia." (PMID 26504362, 2015).
Anorexia (continued). "Although the catabolism is mainly mediated by the effects of certain cytokines, such as tumor necrosis factor-α (TNF-α), interleukin-1β (IL-1β), and interleukin-6 (IL-6), the mechanisms associated with cancer related anorexia are still not elucidated completely." (PMID 20920199, 2010). "Inflammatory cytokines interfere with hypothalamic appetite control, particularly in the arcuate nucleus: IL-1β and TNF-α reduce neuropeptide Y (NPY) and agouti-related peptide (AgRP), leading to anorexia." (PMID 40927563, 2025). "On the other hand, TNF-α and interferon γ (IFN-γ) have been found to suppress myosin expression in muscle cells and therefore lead to anorexia." (PMID 39997063, 2025). "Pro-inflammatory cytokines, including interleukin-1 (IL-1), IL-6, and tumor necrosis factor-α (TNF-α), have been identified as mediators of anorexia and the breakdown of skeletal muscle protein, which are crucial components of cancer malignant stroma." (PMID 38267975, 2024). "Interleukin-1 (IL-1), IL-6, tumor necrosis factor-alpha (TNF-α), and interferon-γ are demonstrated to contribute to anorexia." (PMID 37492594, 2023). "In this sense, our findings indicate that the acute effects of TNF-α and IL1-β on AgRP-producing neurons likely contributes to the inflammation-induced anorexia since both cytokines inhibit the activity of 35–42% of AgRP neurons recorded." (PMID 33255553, 2020). "In line with that notion, in a cardiac cachexia rodent model, anti-TNF-α treatment significantly reduced losses in body and skeletal muscle mass, partly through reduced UPS activation through the attenuation of anorexia." (PMID 33329046, 2020). "Moreover, the high TNF-α plasma levels shown by anorexic patients may explain the dramatic fall in NO3 after food stimuli due to decreased NO synthesis perpetuating the early anorexia." (PMID 31191339, 2019). "Through increasing gene expression of anorexia-inducing proinflammatory cytokines such as interleukin-1β (IL-1β), interleukin-6 (IL-6) and tumor necrosis factor-α (TNF-α), trichothecenes exacerbate the condition of anorexia." (PMID 29535978, 2018). "Cancer-induced anorexia and cachexia involve proinflammatory cytokines such as IL-6, MCP-1, and TNF-α." (PMID 24963216, 2014). "A number of inflammatory stimuli activate hypothalamic pro-inflammatory cytokines, including tumor necrosis factor-α (TNF- α), interleukin 1-β (IL1-β) and IL-6, which is involved in anorexia and febrile responses." (PMID 21283791, 2011). "Thus, a specific increase of IL-1β in CX3CR1-/- mice without a concomitant exaggeration of TNFα may enhance the behavioral effects of LPS without causing exaggerated anorexia and weight loss." (PMID 21167054, 2010). "Previous studies have shown that TNF-α and IL-1β play an important role in the induction of anorexia by DON and its congeners and that the use of antagonists of the TNF-α receptor as well as the IL-1β receptor also attenuates DON-induced anorexia." (PMID 39691381, 2024). "In patients with cancer cachexia, cytokines, such as interleukin (IL)-1, IL-6, and tumor necrosis factor (TNF)-α, are transported across the blood-brain barrier, and induce anorexia by modulating the hypothalamic areas of the brain, the key region for appetite regulation." (PMID 30754663, 2019). "Although central TNFα levels were not directly monitored, the 20 pg/ml serum TNFα measured during secondary hypophagia is below the levels required to induce anorexia by central administration." (PMID 23349631, 2013). "We did not observe a reduction of potentially TNF-α mediated constitutional symptoms, such as anorexia or lethargy." (PMID 20842130, 2010). "A single dose of TNF-α could increase muscle proteolysis and lead to anorexia in rats, whereas nutrient intake and body weight were markedly improved in tumor-bearing rats receiving TNF-α inhibitors, which suggests that TNF-α exerts a vital role in the induction of anorexia." (PMID 36139760, 2022).
Anorexia (continued). "This was not due to TNF-induced anorexia or altered food consumption due to elevated leptin levels." (PMID 27045690, 2016). "It was thus not due to TNF-induced anorexia since TNF was genetically absent or to elevated leptin levels as has been hypothesized for human children with UC, since T/I mice ate more chow than their T/I-het littermates or WT mice." (PMID 27045690, 2016). "It has been reported that NF-κB and C/EBP DNA binding activity are responsible for TNF-α induced IL-6 expression via PPAR-γ, and inhibition of PPAR-γ might be the reason for decreased levels of TNF-α induced IL-6 expression which are mediators of anorexia." (PMID 24381940, 2013). "In addition, exogenous IL-1β and TNF-α did not induce anorexia individually, but did so when administered simultaneously by causing neuroendocrine changes." (PMID 24209779, 2013).